CD4 (CD4 molecule)
Diseases named in the same sentence as CD4 in open-access papers (continued):
Sharing a sentence is not in itself a finding about the gene and the disease.
cancer (continued). "Moreover, AKT-inhibited CD8+ T cells should be expanded in the absence of CD4+ T cells, where CD4+ T cells could be expanded separately with or without AKT-inhibition, followed by co-infusion for therapy of cancer patients." (PMID 32504246, 2020). "The experience accumulated in the field of cancer therapy with immune checkpoint inhibitors provides evidence that the microbiota govern the balance between CD8+ T cell activation and inflammation on one side and CD4+/FoxP3+ T reg cells and lack of inflammation on the other side." (PMID 32793150, 2020). "Neither CD4+ T cell nor CD8+ T cell could predict the prognosis (P=0.9032 and P=0.0701, respectively), although there was a trend for higher CD8+ T cell numbers in carcinoma tissue correlated with a positive prognosis." (PMID 31777600, 2019). "Notably, after 24 hours of coincubation with FRα-expressing cancer cells (SKOV3), C4-27z and C4opt-27z, but not CD19-27z, CAR expression declined rapidly in CD3+, CD4+ or CD8+ T cells, consistent with T cell activation and metabolism resulting in a greater loss of RNA-transcribed CAR expression." (PMID 26359629, 2015). "Of these, the MHC II-restricted peptide-epitope, NY-ESO-187-111-specific CD4+ T-cell was characterized in the context of HLA-DRB3*0101, indicating that bvPLA2m allows NY(s) presentation by the DCs without impairing the processing of the natural cancer/testis antigen, NY-ESO-1." (PMID 23825678, 2013). "Additionally, the ratios of CD8+/CD4+ regulatory T cells displayed a significant negative correlation with ITH scores by MATH, PhyloWGS, ABSOLUTE, DEPTH, and tITH in 9, 9, 6, 21, and 21 cancer types, respectively, compared to DEPTH2 in 18 cancer types (P < 0.05)." (PMID 35365157, 2022). "In addition, on the basis of CD4 count or drug-druginteractions, oncologists might choose alternate anticancer agents or modify dosingor timing with ART initiation, regardless of whether the cancer is consideredassociated with HIV." (PMID 30241139, 2018).
bacterial infections (246 papers, 2007 to 2026). "Taken together, these data show that short-term dietary changes lead to higher susceptibility to mucosal and systemic bacterial infections and impair antigen-specific CD4+ T cell immunity to model antigens." (PMID 37580603, 2023). "The selective expression of T-bet is essential in Th1 development, and previous studies have shown that T-bet deficient CD4+ T cells fail to trigger an effective Th1 response during bacterial infections." (PMID 34659221, 2021). "In univariable analysis, higher time-updated CD4 cell count (0·78, 0·71–0·85, p=0·0001) was associated with reduced risk of severe bacterial infection." (PMID 28063815, 2017). "Immediate ART initiation reduced the risk of severe bacterial infections in asymptomatic HIV-positive people with high CD4 cell counts by 61%." (PMID 28063815, 2017). "The time-updated CD4 cell count remained strongly associated with a reduced risk of severe bacterial infection (0·84, 0·76–0·93, p=0·0006) when time-updated values were delayed by 6 months." (PMID 28063815, 2017). "We also aimed to characterise the factors associated with risk of severe bacterial infection in this multiregional study of people with high CD4 cell counts." (PMID 28063815, 2017). "Immediate ART reduces the risk of several severe bacterial infections in HIV-positive people with high CD4 cell count." (PMID 28063815, 2017). "Higher time-updated CD4 cell count was associated with a reduced risk of severe bacterial infection (0·78, 0·71–0·85, p=0·0001)." (PMID 28063815, 2017). "Next, we examined the ability of CD4-MyD88-deficient mice to eliminate intracellular bacterial infections." (PMID 28817719, 2017). "In this study, we aimed to quantify the effects of immediate versus deferred ART on the risk of severe bacterial infection in people with high CD4 cell counts in a preplanned analysis of the START trial." (PMID 28063815, 2017). "The French Perinatal Cohort showed an association in HEU infants between serious bacterial infections and maternal CD4 count near delivery." (PMID 27199989, 2016). "On bacterial infection, the deficiency of Clec4A4 not only led to the augmentation of anti-bacterial CD4+ Teff cell-responses, but also displayed the prominent elimination of the invaded bacteria, resulting in the reduction of the mortality." (PMID 27068492, 2016). "This association was further supported by a recent multicentre retrospective study conducted in France and showing a significant association between low maternal CD4+ cell count and risk of bacterial infections in infancy." (PMID 26284528, 2015). "Decreased numbers of CD3+ and CD3+CD4+ helper T lymphocytes affect the body’s ability to remove pathogens and are likely associated with persistent bacterial infections in the lower airway and the prolonging of disease." (PMID 26338462, 2015). "The most frequently reported problems have been bacterial infections, with CD4+ T lymphocyte count and viral burden as underlying risk factors." (PMID 25662560, 2015). "Conversely, in the spleen, the immune environment was shifted toward a mixed Th1/Th17 response, with increased IFNγ and IL-17A-producing CD4+ T cells, a hallmark of bacterial infection." (PMID 24945934, 2014). "Studies of immune function in mice deficient in OX40 and CD30 reveal that although CD4 immunity is reduced, deficient mice are able to deal with the common viral and bacterial infections that can be associated with conventional immunosuppressive strategies." (PMID 24782861, 2014). "A single intraperitoneal (IP) injection of 100 μg lipopolysaccharide (LPS), used to mimic a bacterial infection, caused a significant reduction in the percentage of CD4+CD8+ (DP) thymocytes within 24 h." (PMID 22110677, 2011). "The significance of this finding remains unclear, but it could reflect increased susceptibility to bacterial infections in the setting of low CD4 counts or microbiome changes that influence immune function." (PMID 30315476, 2018).
bacterial infections (continued). "Interestingly, we have shown for the first time that a CD4/CD8 ratio <0.8 was associated with an increased risk of bacterial infection." (PMID 27050752, 2016). "In addition, concomitant bacterial infections and low CD4 counts were associated with increased ATB risk." (PMID 23936478, 2013). "The decrease in proliferation of CD4+T cells may indicate suppressive effects of cigarette smoke on immune responses and may account for the higher susceptibility of smokers to viral and bacterial infections." (PMID 19293939, 2009). "The logistic regression model emerged as the optimal model for predicting recurrence of NPM with machine learning, primarily utilizing three variables: FIB, bacterial infection, and CD4+ T cell count." (PMID 39820962, 2025). "CD4+ T cells exhibit increased and sustained PD-1 expression during bacterial infection in mice and humans." (PMID 39745465, 2025). "The top three indicators (FIB, bacterial infection, and CD4+ T cell count) were filtered and used to build the model." (PMID 39820962, 2025). "In the absence of CD4 Th1 cells, M. tuberculosis can disseminate despite intact granuloma structure, meaning that effective control of bacterial infection necessitates the involvement of antigen-specific CD4+ T cells." (PMID 40237474, 2025). "A low CD4+ T-cell count weakens cellular immunity, which is essential to keep bacterial infections under control, particularly in deep tissue such as bone and joint spaces." (PMID 40507649, 2025). "CD4 molecules are mainly expressed on the surfaces of the thymus and mature T cells, where they play an important role in host resistance to viral and bacterial infections." (PMID 39045327, 2024). "Vaccinated mice treated with FTY720 maintained protection against P. aeruginosa, which aligns with findings that only transferring pulmonary CD4 or γδ T cells is sufficient to control pulmonary bacterial infection." (PMID 39556597, 2024). "Second, we focused on the expression of co-inhibitory molecules and cytokines on CD4+ lymphocytes in this study, as CD4+ lymphocytes play vital roles in defense against bacterial infections." (PMID 39104530, 2024). "Remarkably, whereas 90% of control mice tolerated the DSS-treatment only 33% of IF1-KO mice survived, supporting the idea that the CD4+ guided adaptive immune response is compromised in IF1-KO mice upon a bacterial infection." (PMID 38799559, 2024). "One of the most widely studied cytokines in the context of bacterial infections is interleukin 17 (IL-17), produced by the Th17 subset of CD4+ T cells." (PMID 38474048, 2024). "HIV-1 seropositive specimens were obtained from patients receiving Cotrimoxazole prophylaxis, which is routinely administered to patients with low CD4+ T-lymphocyte counts in order to prevent potentially fatal bacterial infections." (PMID 37153598, 2023). "Antigen-specific CD4 + T cell lytic activity mediated by GrB can be triggered by viral and bacterial infections." (PMID 38072840, 2023). "CD4+ T cells are important for orchestrating immune responses against bacterial infections, including in the respiratory tract." (PMID 37809107, 2023). "It is generally known that IL-22, particularly IL-22 secreted by CD4 T cells, plays a more important role on the defense against bacterial infection and the protection of intestinal crypt epithelial cells." (PMID 37067423, 2023). "In the early phase of bacterial infections, the percentage of CD4+ regulatory T cells (Tregs) is increased, and adoptive transfer of CD4+ Tregs improves the survival rate." (PMID 37212786, 2023). "For example, NLRC3 genes contribute to thymic development but suppress the functions of CD4 + T cells in the spleen of mice during bacterial infection." (PMID 37964222, 2023). "Together our study highlights a beneficial role for inflammation in the development of CD4+ T cell-mediated immunity and identifies IMs as a potential target for enhancing T cell immunity to intracellular bacterial infection." (PMID 37733817, 2023).
bacterial infections (continued). "Furthermore, initiation of cART is reported to dramatically reduce the risk of severe bacterial infection even in PWH with CD4+ T cell count > 500 cells/μL which may indicate a role for an improved innate response in line with our finding of improved LPS-induced responses." (PMID 36059528, 2022). "Several studies have shown that during bacterial infections, Notch signaling pathways modulate the CD4+ T cells' function and regulate T cell polarization." (PMID 35274021, 2022). "Previous work indicates that in response to acute viral or bacterial infection, the majority of pathogen-specific CD4+ T cell clones can give rise to both Th1 and Tfh cells following clonal expansion." (PMID 36255051, 2022). "HLA-DQ and HLA-DR are major histocompatibility complex (MHC) class II molecules that play a key role in the adaptive immune response, especially against bacterial infections, by presenting pathogen antigens mainly to the CD4 + T helper cells." (PMID 35173190, 2022). "To summarize, microbial antigens, B cell receptors, TLRs, and CD4+ T cells cooperate to activate RF-producing B cells after bacterial infection, and both B cell receptor signaling and CD4 T+ cell help are critical to enhance the RF secretion." (PMID 36385263, 2022). "Peripheral CD8+ and CD4+ T-cell numbers were unchanged in malnourished children with bacterial infections, but some memory T-cell subsets appeared to be reduced." (PMID 36297116, 2022). "The expressions of Zbtb7b and RUNX3 restrict each other, affect the response of CD4+ T cells, and impair intestinal inflammatory immunity and the probability of exogenous bacterial infection." (PMID 35761286, 2022). "Several studies have previously shown that human pleural mesothelial cells upregulate their ICAM-1 expression and serve as chemokine sources in response to bacterial infection, thus directly participating in the recruitment of monocytes and CD4+ T cells." (PMID 35418979, 2022). "Patients with advanced HIV disease had a higher proportion of bacterial infections (55/76 (72%) if CD4 ≤200 cells/mm3 and 25/52 (48%) if CD4 >200 cells/mm3, p 0.02)." (PMID 32896654, 2021). "On a molecular level, bacterial infection led to STAT3 activation in the colon of these animals which in turn leads to a Th17 response characterized by IL-17-secreting CD3+CD4+ and CD3+CD4– cells." (PMID 34658896, 2021). "Single-cell RNA sequencing of the lung from mice with bacterial infection has revealed the enhanced expression of Il7 by lymphatic endothelial cells, which are colocalized with CD4+ T cells." (PMID 33968018, 2021). "Patients with advanced HIV disease had a higher proportion of bacterial infections (55/76 (72%) in those with CD4 ≤200 cells/mm3 and 25/52 (48%) in those with CD4 >200 cells/mm3, p 0.02)." (PMID 32896654, 2021). "A parallel bifurcation between humoral and cell-mediated immunity in peripheral tissues can also be gleaned from CD4+ T cell responses to viral or bacterial infection." (PMID 34106992, 2021). "Since their identification, it has become well-known that CD4+ TH17 cells are fundamentally important for driving immune responses against bacterial infection, along with CD4+ TH1 subsets." (PMID 32858901, 2020). "MHC class II-restricted CD4+ T cells are important for protective immunity against a range of bacterial infections and provide a vital source of cytokines that help to facilitate such anti-bacterial immunity." (PMID 32858901, 2020). "We assessed the intact Ag-specific CD4+ T cell response after primary and secondary bacterial infection." (PMID 32983171, 2020). "Using the CIBERSORT method, we also found that ACLF was associated with a systemic depletion of resting memory CD4 T cells which may play a role in systemic immunosuppression in this syndrome; thus, memory CD4 T cells are essential for an immediate response against bacterial infections." (PMID 33613548, 2020).
bacterial infections (continued). "Cytolytic CD4+ T cells are currently under intense investigation regarding their role during viral/bacterial infections, autoimmune conditions and solid tumor malignancies." (PMID 31440240, 2019). "Atlantic cod lacks the genes for MHC-II, the invariant chain/CD74 (Ii), and CD4+ T cell response, representing a paradigm in the context of adaptive immunity against bacterial infectious diseases." (PMID 31231379, 2019). "HIV-infected participants with a CD4 count < 200 demonstrated an 11.6-fold increased odds and 10.4-fold increased odds of bacterial infection at 3 months and 6 months, respectively." (PMID 31208419, 2019). "The MHC-II binds antigens from extracellular pathogens, and the MHC-II-antigen complex activates helper CD4+ T cells, which play an essential role fighting bacterial infectious diseases." (PMID 31231379, 2019). "HIV-infected participants with a CD4 count > 500 cells/ml had a 3.7-fold increased odds and 3.5-fold increased odds (95% confidence interval [CI], 2.30–5.39) of bacterial infection at 3 months and 6 months, respectively." (PMID 31208419, 2019). "This lineage CD4+ T cell produces unique cytokines IL-17A and IL-22, which play roles in inflammation pathogenesis and against extracellular fungi and bacterial infection." (PMID 31001353, 2019). "Previous studies indicate the importance of a CD4+ tissue-resident memory response for naturally-acquired immunity against bacterial infections." (PMID 31708925, 2019). "Blockade or knockdown of Cd58 and Cd2 dramatically impaired the activation of antigen-specific Cd4+ T and mIgM+ B cells, followed by the inhibition of antibody production and host defense against bacterial infections." (PMID 29904386, 2018). "By knockdown and blockade of Cd58 or Cd2, the activation of antigen-specific Cd4+ Th cells was significantly impaired, mIgM+ B cell activation and Ab (IgM) production were inhibited, and defense against bacterial infections post-vaccination was diminished." (PMID 29904386, 2018). "Neither trial reported on analyses describing the extent to which the effect on bacterial infections was mediated by changes in CD4 cell count or neutrophil count." (PMID 28063815, 2017). "Immunity against S. Typhi requires the concerted action of both B cell and T cells responses whereby provision of IFN- γ and other cytokines by CD4+ T cells is key for the control of the bacterial infection." (PMID 28570603, 2017). "In this study of 7638 infants, the adjusted HRs for a serious bacterial infection were 1.7 (95% CI 1.2–2.6) and 1.2 (95% CI 0.8–1.9) for infants of mothers with CD4 count below 350 cells/μl and 350–500 cells/μl respectively, compared to above 500 cells/μl." (PMID 27199989, 2016). "To study the T cell-specific function of A20 in bacterial infection, we infected T cell-specific A20 knockout (CD4-Cre A20fl/fl) and control mice with Listeria monocytogenes." (PMID 28004776, 2016). "In our study, treatment for bacterial infection appeared to be useful in individuals with CD4 cell count > 350, or in early stage HIV disease (and therefore not eligible for ART) although some of this lost significance in multivariate analysis." (PMID 27303572, 2016). "Because Treg numbers increased and CD4+ effector T cells decreased, the immune response to bacterial infection seemed to be weakened in TSC1 KO mice." (PMID 27746591, 2016). "A key step to mounting a protective immune response to Mtb and to most bacterial infection is represented by CD4+ and CD8+ T cell priming in lymph nodes." (PMID 28989808, 2016). "We have noticed that, similar to other bacterial infections, CD4 count at the time of occurrence was low and that more than 17% were also diabetics." (PMID 27050752, 2016). "During bacterial infection, the percentage and number of activated effector CD4+ T cells decreased in TSC1 KO mice." (PMID 27746591, 2016).